A2M (alpha-2-macroglobulin)
Diseases named in the same sentence as A2M in open-access papers (continued):
Sharing a sentence is not in itself a finding about the gene and the disease.
Ureteral obstruction (1 paper, 2025). Obstruction of the flow of urine through the ureter. "In vivo, type 1 diabetic Akita mice overexpressing TGF-β1 were treated with either a neutralizing antibody for csGRP78 (C38) or α2M* (Fα2M) or an inhibitory peptide blocking csGRP78/α2M* interaction, and mice with unilateral ureteral obstruction were treated with Fα2M or inhibitory peptide." (PMID 41424384, 2025).
vitiligo (1 paper, 2022). Generalized well circumscribed patches of leukoderma that are generally distributed over symmetric body locations and is due to autoimmune destruction of melanocytes. "Moreover, A2M and TGM2 upstream regulators were also found to be differentially expressed in vitiligo samples." (PMID 35406685, 2022). "However, little is known about the function of A2M and TGM2 in vitiligo, which needs to be explored in the future." (PMID 35406685, 2022). "A2M and TGM2 were predicted to be the inhibitory upstream regulators of the DEARGs in vitiligo." (PMID 35406685, 2022). "Moreover, A2M and TGM2 were shown to be downregulated in vitiligo lesions from our RNA-seq dataset, which more favorably indicates that their decreased expression might subsequently cause the expression alterations of the downstream DEARGs." (PMID 35406685, 2022).
cancer (47 papers, 2012 to 2025). A tumor composed of atypical neoplastic, often pleomorphic cells that invade other tissues. "Association of cell surface GRP78 with α2M* is involved in the regulation of cell proliferation, survival and apoptosis in human cancers." (PMID 25958313, 2015). "a2M plays diverse and complex roles by binding to different hormones and regulating their activity; several studies on the association between a2M and cancer have indicated that the former might play an important anti-tumor role." (PMID 36176383, 2022). "In IDC, A2M expression was elevated in tumor tissues and correlated with a higher tumor grade and poorer survival, suggesting a role in cancer progression." (PMID 40649877, 2025). "A2M, as a protease inhibitor, is involved in the degradation of extracellular matrix components, a significant process in cancer cell invasion and metastasis." (PMID 40649877, 2025). "The presence of the T-antigen in these glycoproteins was confirmed by tandem mass spectrometry, as highlighted by the MS/MS spectra for cancer-related glycoproteins alpha-1-acid glycoprotein 1 and alpha-2 macroglobulin." (PMID 38612533, 2024). "Among them, TIMP1, LGALS3BP, A2M, AHSG, FN1, HRG, and ITIH4 have been associated with cancer, while CF I, C2, and C4A, have been related to complement activity." (PMID 37685286, 2023). "The pan-cancer survival network further enriches the inhibition of matrix metalloproteases (A2M, MMP1, MMP14, MMP3, TIMP4)." (PMID 35106465, 2022). "Taking advantage of the immunoaffinity of A2M protein complex in human serum, more and more studies have taken A2M protein complex as a new cancer serum biomarker." (PMID 35614936, 2022). "We selected the malignant tumor-specific SE-regulated gene A2M and the conservative SE-regulated gene ABALON as representatives and displayed the H3K27ac signal distribution on the two loci by IGV in the eight common malignant tumor cell lines." (PMID 34722892, 2021). "A2M, which is involved in the Fas apoptotic signaling pathway, was upregulated in 18 cancers in the high-invasiveness score group and negatively correlated with sensitivity to eight drugs, such as Axitinib (r = − 0.503) and Dabrafenib (r = − 0.494)." (PMID 33766047, 2021). "Overexpression of α2M has been detected in different types of cancers and functions as a regulator of many signaling pathways." (PMID 32559179, 2020). "A2M’s role in cancer biology is likely due to its ability to act as a signalling molecule and transporter of growth factors, such as TGFβ and IL6, and as a modulator of protease activity." (PMID 32927694, 2020). "The normalized areas were statistically analyzed by our paired setup and the higher abundance in cancer samples were confirmed to pyruvate kinase, alpha-2-macroglobulin, and complement factor B (p-value < 0.05)." (PMID 30999875, 2019). "We stimulated multiple cancer cell lines with α2M* and acetate alone or in combination in the absence and presence of AKTi, ACLYi, and C38 Mab and probed for the indicated proteins." (PMID 29296215, 2017). "To investigate the mechanism by which the α2M*/CS-GRP78 axis regulates acetyl-CoA production under hypoxia we treated different cancer cell lines with C38 Mab under hypoxia and then stimulated with α2M* and acetate." (PMID 29296215, 2017). "Here, we demonstrate that α2M*/CS-GRP78 signaling regulates cancer cell by utilizing glucose and acetate as a carbon source for the production of acetyl-CoA." (PMID 29296215, 2017). "In cancer cells ACLYi alone suppressed α2M*-induced acetyl-CoA production whereas acetate restored this event which indicates that ACSS1 can compensate depending on acetate availability." (PMID 29296215, 2017). "Beyond the role as a pro-proliferative signaling mechanism, our findings highlight an epigenetic role for the α2M*/CS-GRP78 axis in metabolic adaptation of cancer cells." (PMID 29296215, 2017).
cancer (continued). "The identification of bonafide and protective tumor antigens (that is whole protein or derivative peptides) in blood and the pre-formation of α2M-tumor antigen complexes would generate an effective vaccine for treatment of various cancers." (PMID 23226267, 2012). "We examined the effectiveness of α2M in cancer immunotherapy and observed that α2M-peptide complexes prime immune responses that retard the growth of established tumors in mice." (PMID 23226267, 2012). "Additionally, genes like ACTA1, COL4A3, A2M, ADRB2, MYOC, among others, are closely associated with cancer biomarkers, candidate prognostic factors, and therapeutic targets." (PMID 39968416, 2025). "Alpha-2-macroglobulin (A2M) was also observed, which is a known protease inhibitor but it also functions as a non-specific carrier for various cytokines and growth factors, perhaps implicating its contributions to cancer as a part of the niche." (PMID 37759310, 2023). "Furthermore, enzyme-linked immunosorbent assay of uEVs isolated from patients with BC (n=60) and non-cancer control subjects (n=23) validated the significant upregulation of a2M expression in patient uEVs (p<0.0001)." (PMID 36176383, 2022). "Importantly, it has been reported that activated A2M signals promote the proliferation and survival of cancer cells predominantly through cell surface GRP78 (CS-GRP78)." (PMID 33494824, 2021). "Although α2M was reported to be able to play an oncogenic role in cancers, it remained unclear whether α2M was involved in GALNT6 promoting metastasis, or whether GALNT6 could mediate mucin-type O-glycosylation of α2M." (PMID 32559179, 2020). "We treated the various cancer cell lines with C38 Mab and AKTi and then stimulated with α2M*." (PMID 29296215, 2017). "To determine whether AKTi-induced acetyl-CoA synthesis affects histone acetylation we treated the various cancer cell lines with C38 Mab and AKTi alone or in combination and then stimulated with α2M*." (PMID 29296215, 2017). "Cancer tissues were demonstrated to express latent forms of metalloproteinases and show decreased expression of metalloproteinase inhibitors, such as tissue inhibitors of metalloproteinases (TIMPs) and alpha-2-macroglobulin." (PMID 27406386, 2016). "We next assessed whether α2M* modulate the metastasis of cancer cells using wound healing assay and found that stimulation with α2M* significantly facilitated the metastasis of QGY-7703 and PLC cells." (PMID 25958313, 2015). "When activated, α2M binds directly with corresponding cell surface receptors and functions as a regulator of many signaling pathways and plays a growth factor-like role in many human cancers." (PMID 25958313, 2015). "Both A2M and PDGFRA with underexpression and somatic mutation can lead to the cancer development." (PMID 25137136, 2014). "As such, LINC00987 and A2M might be key factors in treatment strategies against these cancers." (PMID 33987201, 2021). "SPARC+ T cells highly expressed the genes responsible for extracellular matrix formation, SPARC, VEGFA, A2M and COL4A126, thus implicating an important role in cancer development and metastasis." (PMID 37550396, 2023). "For patient ID 110, this notably included MAP2K2, KIT, VEGFA, A2M, ICAM1 and PLA2G4A, all of which are involved in cancer development." (PMID 34771574, 2021). "Here, we demonstrate that the α2M*/CS-GRP78 axis regulates acetyl-CoA synthesis and thus functions as an epigenetic modulator by enhancing histone acetylation in cancer cells." (PMID 29296215, 2017). "We found also several genes underexpressed in subset of cancer samples like KLK3, FOLH1, SPON2, A2M, and PCP4." (PMID 22811706, 2012). "Subsequently, the A2M protein expression level was verified in 70 RCC tumor tissue samples from clinical patients of the First Affiliated Hospital of Jinan University and 6 control para-cancer tissue samples using IHC staining." (PMID 40740229, 2025).
cancer (continued). "Our DGE analysis of non-responding gene expression areas provides some initial molecular detail and shows an upregulation of genes involved in migration, resistance, immunosuppressive function, inflammation, cancer, and tumor stroma (e.g., H2AFJ, FKBP2, MGP, A2M, and IGFBP7)." (PMID 36115838, 2022). "We focused on A2M not only because its expression level in CD9+ cells was high but also because activation of A2M signaling was reported to promote the proliferation and survival of cancer cells." (PMID 33494824, 2021). "The role of proteinase inhibitors in connection with cancer protection considered a number of different inhibitors, and the specific role of α2M remains vague since α2M is incorporated in normal but not in tumor cells." (PMID 31824660, 2019). "To test whether α2M*/CS-GRP78 signaling regulates AKT activation to modulate histone acetylation, we treated the various cancer cell lines with C38 Mab and then stimulated with α2M* and acetate either alone or in combination." (PMID 29296215, 2017). "A specific role of A2M in cancer cell metabolism and development has not been elaborated in detail yet." (PMID 29281661, 2017). "Besides functioning as a pro-proliferative signaling pathway, the α2M*/CS-GRP78/AKT axis regulates glucose and acetate-derived acetyl-CoA production to induce histone acetylation levels and function as an epigenetic metabolite to promote cancer cell survival and proliferation." (PMID 29296215, 2017).
tumor (42 papers, 2012 to 2025). "In particular, these highly expressed genes were notably associated with tumor development and metastatic progression, including A2M, AREG, chemokines (iCAFs-S1), BGN, MFAP5, THBS2, and TIMP1 (iCAFs-S2)." (PMID 39323622, 2024). "Due to differences in localization of α2M (blood) and tumor antigens (cell associated), α2M-antigen complexes cannot routinely be purified directly from the tumor as is done for HSPs." (PMID 23226267, 2012). "Our studies conclude that, α2M associates with tumor antigens in vivo and that these α2M-peptide complexes are therapeutically effective against established tumors." (PMID 23226267, 2012). "Tumor antigens associated with α2M are expected to be a tiny percentage of the total repertoire of peptides and will be randomly extended variants of the final MHC I presented peptide." (PMID 23226267, 2012). "Assuming the proposed protective role of this protein in humans it might become clear now that a progressive A2M deficiency may abet tumour development especially under the view that most tumours develop in slow motion over a time period of about 10–20 years." (PMID 29281661, 2017). "In addition, we tested and showed that the association of tumor-derived antigenic peptides with α2M occurs naturally in mice as these complexes can be purified intact without manipulation in vitro." (PMID 23226267, 2012). "The protein encoded by A2M is alpha-2-macroglobulin, which may promote tumor progression in mice." (PMID 35300428, 2022). "A2M protein expression level was verified in combination with tumor samples from 70 clinical RCC patients." (PMID 40740229, 2025). "This study revealed that A2M played an important role in tumor immune regulation and was closely related to NK cells, MNPs, and T cells." (PMID 40740229, 2025). "In vitro and in vivo experiments on model objects show tumor suppression functions for the A2M protein." (PMID 38254997, 2024). "Recently, A2M has been shown to influence tumour cell adhesion, migration, and growth by inhibiting tumour-promoting signalling pathways, e.g., PI3K/AKT and SMAD, and upregulating PTEN." (PMID 38612805, 2024). "Gene Set Enrichment Analysis revealed that A2M promoted tumor development through enhancing immune cell related signal pathways, while CD163 and FPR1 inhibited tumor development through activated carcinogenic signal pathways." (PMID 38115318, 2023). "Alpha-2-macroglobulin activates lipogenesis processes that are necessary for the active proliferation and survival of tumor cells." (PMID 37509426, 2023). "These included well-known receptor tyrosine kinase genes (EGFR, TEK and OSMR) that activate MAPK and PI3K signaling pathways, and other tumor-promoter genes (ATP8B2, DAAM1, SLAMF8 and SRGN) as well as tumor-suppressor genes (A2M, DAPK1, RASSF8 and SOCS3)." (PMID 37190308, 2023). "The expression of A2M mRNA was low in tumor parts compared with normal parts, and so were lymph node metastasis and tumor stages." (PMID 35625488, 2022). "Meanwhile, it has been highlighted that increased level of alpha-2-macroglobulin modulates tumour cell adhesion, migration, development and growth by inhibition of tumour promoting signalling pathways." (PMID 35190572, 2022). "Comprehensive bioinformatic analysis showed that the LINC00987/A2M axis is a functional and effective tumor suppressor and biomarker for assessing the immune microenvironment and prognostic and therapeutic evaluations of LUAD." (PMID 33987201, 2021). "Activated α2-Macroglobulin (α2M*) signals through tumor Cell Surface GRP78 (CS-GRP78) to regulate tumor cell proliferation through multiple signaling pathway." (PMID 29296215, 2017). "We recently showed that the α2M*/CS-GRP78 axis regulates ACLY-dependent lipogenesis through the AKT pathway for the proliferation of glycolytically converted tumor cells." (PMID 29296215, 2017).
tumor (continued). "It has been recently shown that A2M is capable to mediate anti-cancerous effects by fostering tumor antigen presentation in tumor bearing mice." (PMID 26103567, 2015). "It is worth to note that QGY-7703 cells treated with PP2 alone share similar inhibitory extent on tumor invasion as compared with cells pretreated with PP2 followed by α2M* stimulation." (PMID 25958313, 2015). "α2M was purified from blood of mice bearing a dorsal ∼15 mm MethA tumor or bearing 4 day MethA ascites." (PMID 23226267, 2012). "We have thus been encouraged by the results presented here showing the effectiveness of α2M in immunotherapy of tumor disease in mice." (PMID 23226267, 2012). "CMS5-derived peptides alone or α2M complexed to irrelevant peptides were unable to affect tumor growth demonstrating the requirement for the CD91/LRP-1-binding chaperone and the specificity provided by the peptides." (PMID 23226267, 2012). "The exact mechanism by which α2M, isolated from blood of tumor bearing mice, elicits tumor-specific immunity is under investigation." (PMID 23226267, 2012). "Taken together, these results suggested that A2M may be involved in the regulation of tumor microenvironment by MNP and T cells in ccRCC, thus affecting immunotherapy response." (PMID 40740229, 2025). "The potential role of A2M in tumorigenesis and tumor progression was further explored." (PMID 40740229, 2025). "Additionally, A2M can also regulate the tumor microenvironment and affect the efficacy of immunotherapy." (PMID 40740229, 2025). "However, the specific mechanism of A2M in regulating the activity of NK cells in ccRCC to inhibit tumor growth remains to be further studied." (PMID 40740229, 2025). "A2M plays a significant role in immunotherapy by enhancing antigen presentation, thereby improving the immune system's capacity to recognize and eliminate tumor cells." (PMID 40740229, 2025). "TTFields also modulated the hypercoagulable phenotype of GBM cells by suppressing A2M expression and upregulating plasminogen activator genes, both of which influence coagulation and fibrinolysis but may also facilitate tumor cell migration." (PMID 40885689, 2025). "This further confirmed that the role of A2M in ccRCC was closely related to tumor angiogenesis." (PMID 40740229, 2025). "We have defined the top 5 marker genes (ADH1B, CFD (DF), SEPP1 (SELENOP), DCN, and A2M) that could be used for the identification of ADH1B+ CAFs in tumor tissues." (PMID 37848457, 2023). "It displayed that the function of A2M was enriched in antigen processing and presentation, chemokine signaling pathway, natural cell mediated cytotoxicity, and T cell receptor signaling pathway, which were involved in the suppression of tumor development." (PMID 38115318, 2023). "In addition, the expression levels of the A2M protein were low in tumor parts compared to normal ones." (PMID 35625488, 2022). "We thus found that the LINC00987/A2M axis might play an important role in regulating tumor stemness and tumor hypoxia." (PMID 33987201, 2021). "Second, the α2M*/CS-GRP78 axis induced ACLY and ACSS1 expression is then associated with acetyl-CoA production which activates acetylation of histone and proteins for tumor growth." (PMID 29296215, 2017). "Our work also suggests that α2M*/CS-GRP78 signaling modulates the rate of acetyl-CoA generation by salvage pathways independent of ACLY which can be sufficient to maintain macromolecular synthesis that supports tumor growth." (PMID 29296215, 2017). "Our results suggest that mutations that disrupt the interactions of IL-10 with its receptors (IL-10RA and IL-10RB) and α2-macroglobulin (A2M) may enhance inflammation and modulate anti-tumor immunity." (PMID 25056661, 2014). "Serum was harvested from these tumor-bearing mice and α2M was purified." (PMID 23226267, 2012).